PRMT8 (protein arginine methyltransferase 8)
Description:
S-adenosyl-L-methionine-dependent and membrane-associated arginine methyltransferase that can both catalyze the formation of omega-N monomethylarginine (MMA) and asymmetrical dimethylarginine (aDMA) in proteins such as NIFK, myelin basic protein, histone H4, H2A and H2A/H2B dimer. Able to mono- and dimethylate EWS protein; however its precise role toward EWS remains unclear as it still interacts with fully methylated EWS.
Synonyms: HRMT1L3; HRMT1L4
Tractability: Small molecule: a structure with a bound ligand is known; a high-quality ligand is known. Antibody: UniProt places it where antibodies can reach, with high confidence; its Gene Ontology location is reachable by antibodies, with high confidence. PROTAC: ubiquitination databases record sites on it; its protein half-life has been measured; a small molecule that binds it is known.
Target class: Epigenetic regulator; Protein arginine methyltransferase; Writer; Protein methyltransferase
Chemical probes: MS023 (high quality)
Gene: Protein-coding gene on chromosome 12 (3,381,349 to 3,593,977, forward strand). Ensembl gene ENSG00000111218.
Subcellular location: Cell membrane
Gene Ontology:
Molecular function: enzyme binding; histone H4 methyltransferase activity; identical protein binding; protein binding; protein homodimerization activity; protein-arginine N-methyltransferase activity; protein-arginine omega-N asymmetric methyltransferase activity; protein-arginine omega-N monomethyltransferase activity; S-adenosyl-L-methionine binding; S-adenosylmethionine-dependent methyltransferase activity
Biological process: chromatin remodeling; protein homooligomerization; regulation of modification of postsynaptic actin cytoskeleton
Cellular component: cytoplasmic side of plasma membrane; nucleus; plasma membrane
Genetic constraint (gnomAD): Loss-of-function variants: 7 observed, 44.81 expected, observed/expected ratio (o/e) 0.16, 90% interval 0.088 to 0.29. The upper end of that interval is the gene's LOEUF score, 0.29, which puts it in group 1 of 6, group 1 being the genes least tolerant of losing a copy. Missense variants: 219 observed, 513.95 expected, observed/expected ratio (o/e) 0.43, 90% interval 0.38 to 0.48. Synonymous variants: 180 observed, 191.65 expected, observed/expected ratio (o/e) 0.94, 90% interval 0.83 to 1.06.
Homologues: Orthologues: chimpanzee PRMT8 (99% identical), macaque PRMT8 (99% identical), dog PRMT8 (98% identical), mouse Prmt8 (98% identical), rat Prmt8 (98% identical), rabbit PRMT8 (96% identical), guinea pig PRMT8 (94% identical), pig PRMT8 (87% identical), tropical clawed frog prmt8 (86% identical), zebrafish PRMT8 (85% identical), zebrafish prmt8b (84% identical), Drosophila melanogaster Art1 (59% identical), and 1 more. Paralogues in human: PRMT1 (72% identical), PRMT3 (42% identical), CARM1 (32% identical), PRMT6 (30% identical), PRMT2 (29% identical), PRMT9 (21% identical), PRMT7 (20% identical).
Diseases named in the same sentence as PRMT8 in open-access papers:
PRMT8 is named in the same sentence as 21 diseases in open-access papers, as found by Europe PMC text mining. Sharing a sentence is not in itself a finding about the gene and the disease. The quoted sentences say what the papers report.
ovarian carcinoma (4 papers, 2022 to 2025). A malignant neoplasm originating from the surface ovarian epithelium. "Among them, high PRMT8 expression was associated with increased patient survival in patients suffering from breast and ovarian cancer, while the opposite was true in gastric cancer, where high PRMT8 expression was associated with decreased patient survival." (PMID 41154773, 2025). "PRMT8 had been reported to be involved in the prognosis of a variety of tumors, with high expression of PRMT8 associated with a good prognosis in breast and ovarian cancers and poor prognosis in gastric cancer." (PMID 36699465, 2022). "Another study observed that high PRMT8 expression correlated with worse survival in gastric cancer; however, increased survival was observed in patients with breast and ovarian cancer." (PMID 36982660, 2023). "In breast and ovarian cancers, high PRMT8 levels have been associated with improved patient survival, although no increased PRMT8 expression was observed in triple-negative breast cancer." (PMID 40869229, 2025).
breast carcinoma (3 papers, 2016 to 2023). "Previous study indicated that PRMT8 was associated with a poor prognosis via z-score analysis, whereas the Kaplan-Meier plot showed a protective trend for breast cancer." (PMID 36982660, 2023). "This larger dataset also uncovered significant prognostic value associated with PRMT8 and SIN3A as well as confirmed the well-known association of high EZH2 expression levels with poor survival in breast cancer." (PMID 27863398, 2016). "PRMT8 is an enzyme whose exact mechanism of action in breast cancer is poorly understood." (PMID 36982660, 2023). "However, the expression of PRMT8 is clinically related to improved breast cancer survival in the impact on breast cancer proliferation." (PMID 33193750, 2020).
amyotrophic lateral sclerosis (2 papers, 2023 to 2025). Amyotrophic lateral sclerosis (ALS) is a neurodegenerative disease characterized by progressive muscular paralysis reflecting degeneration of motor neurons in the primary motor cortex, corticospinal tracts, brainstem and spinal cord. "Given its role, dysregulation of PRMT8 may be implicated in motoneuron‐related degenerative diseases (such as amyotrophic lateral sclerosis) and neurodevelopmental disorders." (PMID 36914965, 2023). "PRMT8 contributes to stress tolerance in motoneurons, preventing degeneration in spinal cord injury (SCI) and amyotrophic lateral sclerosis (ALS)." (PMID 40869229, 2025).
Anxiety (2 papers, 2021). Intense feelings of nervousness, tension, or panic often arise in response to interpersonal stresses. "Indeed, the Prmt8-deficient mice display altered anxiety levels in open field test and elevated plus maze test, while sociability is not affected." (PMID 34833008, 2021). "Despite the observations that Prmt8-deficient mice exhibited selective abnormal behaviors in motor performance and anxiety test, the in vivo role of PRMT8 in brain function has not yet been well defined, and its precise linkage with diseases is largely unexplored." (PMID 34833008, 2021).
colon cancer (2 papers, 2020 to 2025). "Because PRMT8 is highly expressed in colon cancer stem cells, it may be able to influence the expression of Oct4 and Nanog multipotent transcription factors by preventing Sox2 degradation and raising Sox2 protein content through Sox2 methylation." (PMID 41154773, 2025). "PRMT8 may prevent the features of colon cancer stem cells from developing." (PMID 41154773, 2025).
cardiac hypertrophy (1 paper, 2022). "In our study, we found that the mmu-Ryr2_0040---miR-103-3p---Celsr2/Prmt8 axis may be a novel target in cardiac hypertrophy." (PMID 36003513, 2022).
Cognitive impairment (1 paper, 2022). Abnormal cognition is characterized by deficits in thinking, reasoning, or remembering. "Along with the evidence that variant rs12322215 is linked to the promoter region of PRMT8, we conclude that PRMT8 is another biologically plausible gene regulated by eQTL at the TEAD4 locus that could have potential effects on cognitive impairment among preterm children." (PMID 35240980, 2022).
endometriosis (1 paper, 2025). The growth of functional endometrial tissue in anatomic sites outside the uterine body. "DNA hypermethylation of the PRMT8 promoter suggests that altered CpG methylation may repress gene expression, potentially affecting oocyte quality and contributing to infertility associated with endometriosis." (PMID 40724612, 2025).
glioblastoma (1 paper, 2021). The most malignant astrocytic tumor (WHO grade IV). "However, the mechanism underlying PRMT8 in the pathogenesis of glioblastoma is still unclear." (PMID 34833008, 2021). "Reduced transcript expression PRMT8 is observed in glioblastoma patient tissues, suggesting its downregulation during tumor development in the brain." (PMID 34833008, 2021). "While studies have mostly focused on the neuronal function of PRMT8 in the brain, PRMT8 might be important in glial cells as well, especially in the formation of glioblastoma." (PMID 34833008, 2021).
microcephaly (1 paper, 2021). A congenital or acquired developmental disorder in which the circumference of the head is smaller than normal for the person's age and sex. "Among patients sharing microcephaly a common deleted region in 12p13.32 locus of ~ 300 kb containing two genes CRACR2A (HGNC: 28657) and PRMT8 (HGNC: 5188) could be identified." (PMID 33613193, 2021). "Among patients sharing microcephaly a common deleted region of ~ 300 kb in 12p13.32 locus containing two genes CRACR2A (HGNC: 28657) and PRMT8 (HGNC: 5188) could be identified." (PMID 33613193, 2021).
rhabdomyosarcoma (1 paper, 2022). A rare aggressive malignant mesenchymal neoplasm arising from skeletal muscle. "The expression of PRMT1, CARM1, PRMT5, PRMT7, PRMT8 and PRMT9 were all elevated in rhabdomyosarcoma, CARM1 and its direct interaction with histone acetyltransferase PCAF jointly were also detected to exert an increased expression of myogenin gene and lead to rhabdomyosarcoma cell differentiation." (PMID 35311114, 2022).
thyroid carcinoma (1 paper, 2014). "The arginine methyltransferase PRMT8 is overexpressed in 68% of thyroid carcinoma." (PMID 25484917, 2014).
cancer (7 papers, 2021 to 2025). A tumor composed of atypical neoplastic, often pleomorphic cells that invade other tissues. "The type I PRMT family includes PRMT1, PRMT2, PRMT3, PRMT4, PRMT6, and PRMT8, which have been linked to various aspects of cancer development, including carcinogenesis, metastasis, and drug resistance." (PMID 39699269, 2025). "The gene related to rs144225287 (PRMT8) encodes a protein arginine methyltransferase that can enhance cancer stem-cell function and cell proliferation." (PMID 38003606, 2023). "PRMT8 expression has been reported to have conflicting prognostic implications in different cancer types, with elevated levels being associated with improved patient survival in breast and ovarian cancer, but poorer survival in gastric cancer." (PMID 37627211, 2023). "Intriguingly, somatic mutations and altered expression of the PRMT8 gene have been found in cancer cells outside the brain." (PMID 34833008, 2021). "This is noteworthy because, in mature organisms, PRMT8 prefers to be located in brain tissue, indicating a potential function for dysregulation of PRMT8 in carcinogenesis or the maintenance of cancer cell phenotypes." (PMID 41154773, 2025). "The relationship between PRMT8 expression and cancer prognosis varies across studies and cancer types." (PMID 40869229, 2025). "Beyond the nervous system, PRMT8’s expression and its potential pathogenic roles in various non-neuronal cancers, including breast, cervical, and prostate cancers, are still under exploration." (PMID 40869229, 2025). "Numerous cancer forms have been found to have high levels of PRMT8 expression." (PMID 41154773, 2025). "In GSE14520, the expressions of PRMT1, PRMT3, PRMT4, and PRMT5 were upregulated in cancer tissues, whereas PRMT2 and PRMT8 were downregulated." (PMID 37627211, 2023). "There were four mRNAs not only upregulated in ESCC compared with para-cancer tissues but also in Fu-High compared with Fu-Low: C-Type Lectin Domain Family 12 Member A (CLEC12A), Glutamate Metabotropic Receptor 4 (GRM4), Protein Arginine Methyltransferase 8 (PRMT8), and Peptide YY 2 (PYY2)." (PMID 39471360, 2025). "For group 1, seven of the thirteen novel-loci-related coding or noncoding genes, namely F11/F11-AS1, PFKFB3, PRMT8, FAM66C, NAV2/NAV2-AS1, FRMD4A, and KIAA0232, have been demonstrated to be correlated with the development of HCC or other cancers in many studies." (PMID 38003606, 2023). "The non-neuronal function of PRMT8, especially in the context of cancer progression, warrants further investigation." (PMID 34833008, 2021).
tumor (5 papers, 2021 to 2025). "To identify the PRMT responsible for arginine methylation of NONO in CRC cells, we examined PRMT1, PRMT3, PRMT4, PRMT5, PRMT6, and PRMT8 mRNA and protein levels in paired tumor and adjacent normal tissues." (PMID 33420374, 2021). "Thus, the tissue-specific expression and unique enzymatic activity of PRMT8 allow it to be used as a target for drug development to delay the onset of neurodegenerative diseases and tumor treatment." (PMID 41154773, 2025). "PRMT8 may alter immune recognition and escape by regulating the expression of tumor cell surface molecules, such as PD-L1." (PMID 41154773, 2025). "In this study, PRMT1, PRMT2, PRMT5, and PRMT8 were significantly highly expressed in After Tumor." (PMID 38136558, 2023). "Notably, PRMT1, PRMT2, PRMT3, and PRMT7 exhibited upregulation, while PRMT5, PRMT6, and PRMT8 displayed downregulation in tumor." (PMID 37781030, 2023). "PRMT8 may also affect the inflammatory state in the immune microenvironment by modulating inflammation-related signaling pathways, thereby regulating immune cell function and tumor progression." (PMID 41154773, 2025). "The expression of PRMT1, PRMT3, PRMT4, PRMT5, and PRMT7 was elevated in tumor samples compared to normal tissue, while PRMT2, PRMT8, and PRMT9 were decreased." (PMID 40399547, 2025).
neurodevelopmental disorder (2 papers, 2021 to 2023). A behavioral and cognitive disorder with onset during the developmental period that involves impaired or aberrant development of intellectual, motor, or social functions. "Indeed, a recent paper has reported that the PRMT8 gene is located within a common deleted chromosome region from patients with microcephaly, suggesting its possible role in human brain development and its dysfunction in neurodevelopmental disorders." (PMID 34833008, 2021). "In addition to G3BP1, searching for other RNA-binding proteins that are present in dendrite and synapses as the downstream targets of PRMT8 would be critical for illuminating the multifaceted functions of PRMT8 in neurodegeneration and neurodevelopmental disorders in the future." (PMID 34833008, 2021).
Neurological Diseases (1 paper, 2021). "Recent evidence suggesting the potential role of PRMT8 function in neurological diseases will also be discussed." (PMID 34833008, 2021). "Several recent studies have suggested the link between PRMT8 and neurological diseases." (PMID 34833008, 2021). "Since PRMT8 influences motor behaviors through its phospholipase activity, PRMT8 might represent a potential target for drug discovery in delaying degeneration of motoneurons and treatment for MN-related neurological disorders." (PMID 34833008, 2021).
PRMT8 also shares sentences with these, for which no sentence is quoted: gastric cancer (3 papers); cervical cancer (1); ischemic stroke (1); spinal cord injury (1); triple-negative breast carcinoma (1).